BNIP2 (BCL2 interacting protein 2)
Description:
Implicated in the suppression of cell death. Interacts with the BCL-2 and adenovirus E1B 19 kDa proteins.
Synonyms: NIP2; BNIP-2
Tractability: PROTAC: ubiquitination databases record sites on it.
Gene: Protein-coding gene on chromosome 15 (59,659,146 to 59,689,350, reverse strand). Ensembl gene ENSG00000140299.
Subcellular location: Cytoplasm; Cytoplasm, perinuclear region
Subcellular location (Human Protein Atlas): Cytosol; Nucleoli
Pathways (Reactome):
Developmental Biology: Myogenesis
Gene Ontology:
Molecular function: protein binding; calcium ion binding; GTPase activator activity
Biological process: apoptotic process; negative regulation of apoptotic process
Cellular component: cytoplasm; cytosol; intracellular membrane-bounded organelle; nuclear envelope; perinuclear region of cytoplasm
Genetic constraint (gnomAD): Loss-of-function variants: 27 observed, 35.53 expected, observed/expected ratio (o/e) 0.76, 90% interval 0.56 to 1.05. The upper end of that interval is the gene's LOEUF score, 1.05, which puts it in group 4 of 6, group 1 being the genes least tolerant of losing a copy. Missense variants: 393 observed, 337.85 expected, observed/expected ratio (o/e) 1.16, 90% interval 1.07 to 1.26. Synonymous variants: 141 observed, 112.14 expected, observed/expected ratio (o/e) 1.26, 90% interval 1.1 to 1.45.
Homologues: Orthologues: chimpanzee BNIP2 (100% identical), macaque BNIP2 (99% identical), pig BNIP2 (98% identical), rabbit BNIP2 (97% identical), dog BNIP2 (96% identical), rat Bnip2 (93% identical), guinea pig BNIP2 (92% identical), mouse Bnip2 (89% identical), tropical clawed frog bnip2 (80% identical), zebrafish bnip2 (75% identical), Drosophila melanogaster CG11593 (37% identical). Paralogues in human: ATCAY (55% identical), PRUNE2 (55% identical), BNIPL (47% identical).
Diseases named in the same sentence as BNIP2 in open-access papers:
BNIP2 is named in the same sentence as 14 diseases in open-access papers, as found by Europe PMC text mining. Sharing a sentence is not in itself a finding about the gene and the disease. The quoted sentences say what the papers report.
breast carcinoma (2 papers, 2020 to 2024). "Disruption of ARHGEF2/RHOA signaling (removal of BNIP-2 scaffold) affects breast carcinoma cells migration." (PMID 38200184, 2024). "Depletion of BNIP-2 in MDA-MB-231 breast cancer cells decreases RhoA activity and promotes cell migration." (PMID 32789168, 2020). "S3A), which indicates that BNIP-2 is the limiting factor for breast cancer motility." (PMID 32789168, 2020). "We examined whether BNIP-2 could suppress breast cancer cell migration using transwell migration assays." (PMID 32789168, 2020). "Hence, we examined whether BNIP-2 could promote or suppress RhoA activity in MDA-MB-231 cell, a highly migratory breast cancer cell line." (PMID 32789168, 2020).
Breast Invasive Carcinoma (1 paper, 2020). "From the TCGA-BRCA database, the RNA expression level of BNIP-2 is reduced by about 11% in Breast Invasive Carcinoma (TCGA-BRCA) tissues compared to normal tissues, while neither RhoA nor GEF-H1 has noticeable differences between cancer and normal samples." (PMID 32789168, 2020).
breast tumor (1 paper, 2020). "Consistent with the information from breast tumor microarray datasets, our data showed that BNIP-2 depletion promotes cancer cell migration, while physiological level of BNIP-2 suppresses cell migration." (PMID 32789168, 2020).
cardiac hypertrophy (1 paper, 2022). "Comparing control cells and BNIP‐2 knockdown cells after 3 days of ATRA treatment, we observed significant differences in pathways regulating cardiac signaling (e.g., calcium signaling, cardiac hypertrophy, etc.)." (PMID 35975420, 2022).
colitis (1 paper, 2023). Inflammation of the colon. "The AS events of Bnip2, Traf1, and Traf7 that enriched in apoptotic process in acute colitis models have been verified by PCR." (PMID 37158534, 2023).
neuroblastoma (1 paper, 2015). Neuroblastoma (NB) is the most common solid, extracranial childhood tumor. "BNIP2 and Cdc42GAP homology (BCH) motif-containing molecule at the carboxyl-terminal region 1 (BMCC1) gene is highly expressed in patients with favorable neuroblastoma (NB)." (PMID 25611382, 2015).
prostate carcinoma (1 paper, 2013). A carcinoma that arises from epithelial cells of the prostate gland. "The prostate cancer antigen gene 3 (PCA3) is embedded in an intron of a second gene BMCC1 (Bcl2-/adenovirus E1B nineteen kDa-interacting protein 2 (BNIP-2) and Cdc42GAP homology BCH motif-containing molecule at the carboxyl terminal region 1) which is also upregulated in prostate cancer." (PMID 24040105, 2013).
cancer (4 papers, 2019 to 2023). A tumor composed of atypical neoplastic, often pleomorphic cells that invade other tissues. "In summary, we have shown for the first time that PIP increases the sensitivity of BC cells to apoptosis induced by anti-cancer drugs, which is associated with overexpression of specific pro-apoptotic genes (CRADD, DAPK1, FASLG, CD40, and BNIP2)." (PMID 37085653, 2023). "Since RhoA activity is essential for cancer cell migration and metastasis, we investigated the role of BNIP-2 in MDA-MB-231 cell migration." (PMID 32789168, 2020). "Since BNIP-2 knockdown suppresses RhoA activity, we hypothesized that BNIP-2 knockdown could lead to increased motility of cancer cells through regulation of RhoA activity." (PMID 32789168, 2020). "Through better understanding of scaffold proteins such as BNIP-2 and their roles in the cross-talk between cytoskeleton and signaling, we envisage identifying novel cell migratory markers and pharmaceutical targets in different cancer types." (PMID 32789168, 2020). "Such correlation between BNIP-2 expression level and cell metastasis suggests that the expression level of BNIP-2 could be a marker for the cancer cell metastasis." (PMID 32789168, 2020). "Therefore, it is of interest to investigate whether BNIP-2 can scaffold microtubule-regulated GEF-H1 and RhoA for RhoA-mediated cancer cell migration." (PMID 32789168, 2020).
tumor (4 papers, 2011 to 2021). "It is consistent with our data from the TCGA-BRCA database that BNIP-2 is significantly down-regulated in tumor tissues compared to normal tissues." (PMID 32789168, 2020). "Adding to their biological significance, both BNIP-2 and BNIP-XL are cleaved by caspases, releasing their BCH domains that could lead to apoptosis whereas BNIP-2 is also cleaved by granzyme B during the natural killer cell-mediated killing to tumor cells." (PMID 22479462, 2012).
BNIP2 also shares sentences with these, for which no sentence is quoted: infection (2 papers); colorectal cancer (1); heart diseases (1); hepatocellular carcinoma (1); Sepsis (1).